HGF (hepatocyte growth factor)
Diseases named in the same sentence as HGF in open-access papers (continued):
Sharing a sentence is not in itself a finding about the gene and the disease.
tumor (continued). "HGF/Met signaling is required for normal development and adult homeostasis but is also frequently implicated in cancer, contributing to tumor invasiveness and metastasis." (PMID 25335552, 2014). "In fact, stimulation of tumor cells with HGF causes clustering of integrins at focal contacts, mediates firm attachment and spreading, but does not affect their quantitative expression at membrane level." (PMID 28548071, 2014). "HGF is known to be a potent angiogenic factor and to be associated with a more advanced tumor stage in different malignancies in vivo." (PMID 24887580, 2014). "Early developing tumors were more proliferative and were associated with increased levels of tumor-related growth factors, including increased plasma levels of HGF in tumor-bearing animals." (PMID 24156623, 2013). "Another clinical result showed a strong correlation between expression of HGF/c-Met and abnormal expression of E-cadherin in tumor cells, which can be viewed as both a cause and effect of EMT." (PMID 24325214, 2013). "c-Met, a tyrosine kinase receptor for hepatocyte growth factor (HGF), is associated with metastasis and tumour invasion, decreased survival, and was recently investigated as a marker for CSCs in HNSCC." (PMID 23533441, 2013). "In tumor cells, c-Met activation mediated by HGF causes the triggering of a diverse series of signaling cascades resulting in cell growth, proliferation, invasion, and protection from apoptosis." (PMID 23675455, 2013). "Numerous extracellular signaling molecules are implicated in promoting invasive tumor cell migration including hepatocyte growth factor (HGF), transforming growth factor β (TGF-β), epidermal growth factor (EGF), and lysophosphatidic acid (LPA)." (PMID 23527039, 2013). "There are many cytokines secreted by aHSCs that are associated with tumor invasion and metastasis, ingcluding HGF, EGF, IL-1, IL-2, IL-6, MMP-2, MMP-9, TGF-β, TNF-α, VEGF and Wnt families." (PMID 23622143, 2013). "In a xenograft model, temsirolimus suppressed the growth of PC-9 cells overexpressing the HGF-gene; this was associated with suppression of the mTOR signaling pathway and tumor angiogenesis." (PMID 23690929, 2013). "Expression of HGF and c-Met has previously been detected in human cancer in abnormal stages, and is associated with a high tumor grade and poor prognosis." (PMID 23320110, 2013). "The protein kinase C family (PKC) has been shown to be involved in the expression and function of CXCR4, and is also linked to HGF-induced intracellular signal transduction in tumor cells." (PMID 22242160, 2012). "c-Met interacts with hepatocyte growth factor/scatter factor and has been implicated in tumor invasion and migration including PC-3 cells." (PMID 22235332, 2012). "HGF plays an important role in tumor progression and is associated with the prognosis of various human malignancies, including carcinoma of the stomach, liver, lung and nasopharynx." (PMID 22741575, 2012). "In lung cancer, expression levels of both HGF and c-Met have been associated with advanced tumor stage and worse clinical outcome." (PMID 22639908, 2012). "Several studies have shown an association of serum or tumor associated HGF with the progression of various carcinomas." (PMID 21283737, 2011). "Both tumor cell types express HGF, VEGF-A and PDGF-bb - growth factors implicated in the tumor-directed MSC migration." (PMID 20509882, 2010). "Matriptase is a tumor-associated type II transmembrane serine protease that positively regulates carcinoma metastasis by activating the latent forms of hepatocyte growth factor (HGF) and urokinase-type plasminogen activator (uPA)." (PMID 20652009, 2010). "A number of growth factors, including VEGF, FGF, and HGF, have been implicated as angiogenic growth factors that promote tumor angiogenesis in different types of cancer." (PMID 20454645, 2010).
tumor (continued). "A simple text-mining search shows that HGF is eight-fold more strongly associated with tumor metastasis, whereas IGF1 is three times more strongly associated with drug resistance (χ2 = 564.15, df = 1, p < 0.01; Supplement S5)." (PMID 20011464, 2009). "HGF receptor is a tyrosine kinase encoded by c-met and activation of HGF/c-Met pathway is shown to play a key role in tumor induced angiogenesis." (PMID 18549507, 2008). "The HGF/c-Met pathway is reported to be associated with angiogenesis, which is considered to be essential for tumour growth and metastasis." (PMID 15083185, 2004). "The increased HGF levels were significantly associated with the degrees of histological tumour invasion and venous invasion." (PMID 9043023, 1997). "Interestingly, it was recently shown that the HGF/c-MET signaling axis is implicated in tumor proliferation and metastatic spreading of cancer cells." (PMID 40909947, 2025). "Remarkably, DEN therapy resulted in a greater loss of HGF/c-Met signaling, which may have contributed to the tumor’s rapid growth." (PMID 40149719, 2025). "In addition to its critical role in immune regulation and its close association with tumor therapy, HGF also has a significant impact on tumor cell drug resistance and clinical phenotypic manifestations." (PMID 40136462, 2025). "The exact underlying molecular mechanisms between MET mutation and tumor immune microenvironment were largely unknown, but the intricate role of HGF/MET was multifaceted in cancer." (PMID 40330151, 2025). "For instance, targeting hepatocyte growth factor (HGF)-MET or IGF-1/IGF-1R signaling pathways—both critical for maintaining DTP states mediated through tumor-associated fibroblasts (CAFs) and tumor-associated macrophages (TAMs)—has shown promise in preclinical models." (PMID 40894234, 2025). "Importantly, elevated levels of VEGFB, PDGFRA, MAPK13, and HGF have been previously linked to poor prognosis and aggressive tumor behavior in HCC." (PMID 41002582, 2025). "Moreover, we showed in a model of human HGF knock‐in mice that the pro‐tumour property of ETV1/ERG factors is closely linked to MET activity and proposed a specific molecular signature of this cooperation after conducting a large‐scale transcriptomic analysis." (PMID 39374163, 2025). "Finally, HIF promotes the activation of the c-Met receptor for HGF (hepatocyte growth factor), implicated in cell proliferation, motility and survival, further contributing to tumour aggressiveness." (PMID 40869000, 2025). "The initial impact of cancer‐associated fibroblasts on tumour development depends primarily on the abnormal secretion of various proteins from exosomes, hepatocyte growth factor (HGF), tumour necrosis factor‐α (TNF‐α), interleukin 6 (IL‐6) and transforming growth factor‐β (TGF‐β) are included." (PMID 39950738, 2025). "Expression of HGF was significantly associated with advanced tumor stage (p<0.05)." (PMID 39302921, 2024). "HGF recruits and activates tumor-associated macrophages (TAMs)." (PMID 39201787, 2024). "c-MET-driven HGF secretion recruits myeloid-derived suppressor cells (MDSCs) and tumor-associated macrophages (TAMs), while TGF-β induces fibroblasts to differentiate into cancer-associated fibroblasts (CAFs), creating a barrier against immune cell infiltration." (PMID 39664377, 2024). "The mRNA levels of HGF were associated with advanced tumor stage, a known adverse prognosticator." (PMID 39302921, 2024). "HGF, secreted by mesenchymal cells, facilitates interactions between malignant cells and fibroblasts associated with cancer, fostering a microenvironment conducive to tumorigenesis and tumor progression." (PMID 39029056, 2024). "Oncological outcomes measured were PSA levels, PSA velocity, PSA doubling time, Free/Total PSA ratios, tumour size, surgical margins and cancer cell proliferation rates on surgical pathology, hepatocyte growth factor (HGF) and VEGF levels as well as PCa‐specific and all‐cause mortality." (PMID 37334023, 2023).
tumor (continued). "Among these genes, PED4FIP and MUC20 were noted as frequently mutated in malignant tumors and play a role in tissue damage repair and tumor growth through activation of the HGF‐MET pathway, and some evidence suggests that their mutation and expression levels correlate with prognosis." (PMID 37649308, 2023). "HGF has also been implicated in the regulation of immune responses in different tumor models." (PMID 36915128, 2023). "Furthermore, the correlations analysis revealed that five ARGs were associated with tumor purity or seven important immune cells, especially HGF, TRIM22, and SNRPD1." (PMID 37014321, 2023). "Moreover, more research suggests that some tumor stroma cells, such as CAFs and tumor-associated macrophages, are the main sources of HGF expression and release for paracrine mechanisms." (PMID 37919751, 2023). "By enhancing the immune surveillance and anti-tumor effects, HGF may contribute to reducing the risk of AML development or progression." (PMID 38022627, 2023). "Furthermore, CAF-derived HGF has been detected in multiple tumor types as a positive regulator of cancer progression, thus underlining the important role of differential HGF secretion in the stromal-tumor communication." (PMID 37511344, 2023). "Additionally, macrophages and cancer associated fibroblasts present in the tumour microenvironment can secrete classical EMT-inducing cytokines/chemokines including HGF, SDF1α, EGF, PDGF as well as TGFβ1." (PMID 35203300, 2022). "VEGF, FGF-2 and HGF can recruit and activate tumour-associated macrophages." (PMID 36362718, 2022). "This study found that enhanced expression of c-MET and HGF/SF may be associated with an increased risk for metastasis and tumor recurrence in this patient population." (PMID 36034555, 2022). "In addition, RFA caused the upregulation of PD-1 in tumor-infiltrating T cells by promoting hepatocyte growth factor (HGF) expression, which was inhibited by sunitinib treatment." (PMID 36532071, 2022). "In addition to HGF and FGFs, other soluble factors secreted by CAFs have been implicated in tumor resistance to molecular therapies." (PMID 36324182, 2022). "CAFs also cause tumour cells to secrete factors that stimulate them, such as hepatocyte growth factor (HGF), connective tissue growth factor (CTGF), epidermal growth factor (EGF), insulin-like growth factor (IGF), nerve growth factor (NGF), FGF, and Wnt family members." (PMID 36555218, 2022). "HGF, released by stromal cells, acts as a mediator of interactions between cancer cells and cancer-associated fibroblasts, which are fundamental to creating a tumor microenvironment that promotes tumor development and progression." (PMID 34997350, 2022). "The effects of RFA to the tumor microenvironment could be linked to the activation of IL-6/HGF/c-Met pathway which produce downstream angiogenesis and VEGF production." (PMID 35710408, 2022). "cMET expression correlates with liver metastasis of UM and tumor mutational burden in lung cancer patients, and cMET/HGF signaling has been shown to upregulate indoleamine-2,3-dioxygenase (IDO) 1, a highly immunosuppressive molecule involved in resistance to immunotherapy." (PMID 36761417, 2022). "Moreover, lactate can function as a direct signal instructing cancer‐associated fibroblast that secretes hepatocyte growth factor, thus reducing the sensitivity of the tumours to sorafenib treatment." (PMID 35429101, 2022). "Furthermore, constitutive activation of the HGF/c-MET signaling pathway in cancer patients is linked to tumor aggressiveness, drug resistance, and poor prognosis." (PMID 35630066, 2022). "Finally, the drug resistance of cells is mainly derived from the communication between CAFs and tumor cells, in which tumor cells that produce lactate will cause CAFs to feedback growth factors, such as HGF, to strengthen cell resistance to drug treatment." (PMID 34572451, 2021).
tumor (continued). "Therefore, cancer cells would be dependent on HGF‐producing sources, such as neighboring tumor‐associated fibroblasts or distant endogenous sources." (PMID 33738970, 2021). "HGF could also recruit and accumulate more tumor-associated M2 macrophages in tumors and thus increase the resistance to sorafenib treatment." (PMID 34722310, 2021). "Moreover, in vivo xenograft models of the inhibitor retarded tumor growth thereby implicating EMD1214063 as a promising therapeutic target for high-risk NB via its antagonistic effect on the HGF/c-Met activation." (PMID 34055785, 2021). "This suggests that our findings that HGF positivity is associated with aggressive tumor phenotypes may have consequences for recurrence." (PMID 34344422, 2021). "Moreover, Met deficiency in immune cells can promote tumor progression, and the therapeutic benefit of Met kinase inhibitors is partly weakened by the inhibition of antitumor neutrophils, which require HGF/c-Met activation." (PMID 34970484, 2021). "The proportion of HGF positivity was so high among basal-likes and relatively uncommon among non-basal-likes, leaving these assessments somewhat underpowered, though even in these small strata, the associations with tumor aggressiveness appear consistent." (PMID 34344422, 2021). "The HGF/MET signalling pathway is one of the major causes of tumor cell migration." (PMID 32843066, 2020). "Major inducers of EMT in tumor buds are secreted by tumor-associated stromal components; among these inducers are the hepatocyte growth factor (HGF), EGF and TGF-β, which activate intracellular EMT networks involving SMADs, ERK, MAPK and PI3K/AKT signaling pathways." (PMID 33266161, 2020). "Tumor-associated fibroblasts are able to rework the ECM to include more paracrine HGF." (PMID 32435640, 2020). "Furthermore, high expression of HGF or c-MET was associated with higher histological tumor grade and worse patient outcomes." (PMID 32188473, 2020). "The association between tumor production of HGF and NSCLC survival is also summarized." (PMID 32117721, 2020). "Moreover, Met inhibition suppressed radioresistance in vitro, and elevated tumour levels of HGF and Met were associated with a worse prognosis for rectal cancer patients treated with chemo‐radiotherapy." (PMID 32946618, 2020). "Therefore, compared with IHC detection of HGF, detection of DNA methylation of the HGF promoter was significantly associated with tumor progression and shortened survival time in NSCLC patients." (PMID 31602259, 2019). "Moreover we observed that leukemic B cells start to produce HGF after their co-culture with nurse-like cells (NLCs), a peculiar type of tumor associated monocytes (TAM) present in this disease." (PMID 30642077, 2019). "Dysregulation of cMet signaling–mediated proliferation, apoptosis, and migration through cMet overexpression, MET amplification, MET mutation, or HGF‐induced activation has been widely demonstrated in oncogenic processes across multiple tumor types, including NSCLC." (PMID 31040125, 2019). "While these studies speculated implications with alveolar macrophages, it remains of interest if these findings can translate to tumor associated macrophages since HGF can promote disease through HGF/c-Met signaling in a number of cancers." (PMID 31088471, 2019). "However the aberrant expression of c-MET and of HGF is implicated in neoplastic cells spreading and tumor progression in many solid tumors." (PMID 30642077, 2019). "Other approaches to expand efficacy of HGF/c-Met targeting include combining these agents with inhibitors of the viability or function of stromal cells such as tumor-associated fibroblasts, endothelial cells, or macrophages, or using immunotherapy in combination with HGF/c-Met agents." (PMID 30134579, 2018). "In addition, hepatocyte growth factors (HGF) and annexin A1 released by cancer-associated fibroblasts (CAFs) can restore differentiated tumor cells to stem cell phenotypes." (PMID 30344611, 2018).
tumor (continued). "Moreover, elevated HGF expression levels and overexpression of c-Met are often associated with dismal prognosis due to highly aggressive tumor behaviors and increased tumor metastasis." (PMID 28902178, 2017). "HGF induced activation of MET or mutations in the receptor that lead to constitutive activation stimulate the initiation of many downstream signaling pathways that promote tumor cell growth." (PMID 28696366, 2017). "Cancer-associated fibroblasts are the main source of pro-HGF in the tumor microenvironment, therefore we tested whether inhibitors of pro-HGF activation can overcome fibroblast–mediated resistance to MET-targeted therapy." (PMID 28968967, 2017). "The HGF in the HCC environment may be derived not only from tumor cells (autocrine) but also from cancer-associated cells (paracrine)." (PMID 28587113, 2017). "Immunohistochemistry analysis shows that the HGF/c-Met paracrine pattern is seen in 59.1% of tumors; and that this paracrine signaling is associated with a worse outcome when c-Met staining is more intense at the tumor front." (PMID 29296173, 2017). "As the HGF/MET signaling pathway plays a role in several key processes underlying tumor progression, targeting this pathway is considered a promising therapeutic strategy for the treatment of patients with MET-expressing cancers, including those with NSCLC who have acquired resistance to EGFR TKIs." (PMID 27422720, 2016). "It should be noted that other Nrp1-mediated pathways, particularly VEGFA, semaphorin 3A, and HGF signaling may also play important roles in the overall modalities of how GAMs associate with the tumor microenvironment." (PMID 26755653, 2016). "Furthermore, HGF and c-Met have been implicated in regulation of tumor angiogenesis through the direct pro-angiogenic properties of HGF or through the regulation of pro-angiogenic factors secretion." (PMID 27191264, 2016). "Moreover, HGF can be secreted by Met positive tumour cells, creating an autocrine loop and causing a worse survival outcome." (PMID 27175600, 2016). "Moreover, in concordance with other studies, high MET and HGF copy number in tumours from cohort 2 were associated with higher cell proliferation (SPF)." (PMID 27175600, 2016). "Reduction in HGF due to weight loss correlated with diminished tumor progression or deceleration of tumor latency, depending on whether the diet was initiated at weaning or adult onset, respectively." (PMID 27057482, 2016). "Indeed, the expression of ‘uncleavable’ pro-HGF (generated by mutating the cleavage site at Arg494/Val495 to Asp494/Val495) prevents tumor growth in vivo and metastatic spread of cancer cells." (PMID 27121052, 2016). "However, the exact underlying mechanisms of HGF on tumor initiation and development through epigenetic reprogramming remain elusive." (PMID 26099202, 2015). "Dysregulation of MET receptor tyrosine kinase (RTK), the only known high-affinity receptor for hepatocyte growth factor (HGF), has been implicated in tumor cell proliferation, migration, invasiveness, angiogenesis, and metastasis in a broad spectrum of human cancers." (PMID 25294187, 2015). "Inhibition of NRP-1 function may also result in modulation of signal transduction pathways triggered by growth factors other than VEGF-A, such as PDGF, FGF, EGF, and HGF, which are implicated in tumor progression and are capable of binding NRP-1." (PMID 26090340, 2015). "However, MET receptor is expressed not only by cancer cells but also by tumor-associated stromal cells and it is required for the recruitment of anti-tumor neutrophils in response to HGF." (PMID 26384300, 2015). "It is possible that evaluation of the HGF/c-MET signaling axis in the tumor may indicate the susceptibility of that tumor to show resistance through this pathway." (PMID 26090722, 2015).